MIER2 (MIER family member 2)
Description:
Transcriptional repressor.
Synonyms: Mi-er2; KIAA1193
Tractability: No criterion of Open Targets' tractability assessment is met for any kind of drug.
Gene: Protein-coding gene on chromosome 19 (305,573 to 344,815, reverse strand). Ensembl gene ENSG00000105556.
Subcellular location: Nucleus
Subcellular location (Human Protein Atlas): Cytosol; Nucleoplasm
Gene Ontology:
Molecular function: histone deacetylase activity; histone deacetylase binding; protein binding; transcription corepressor activity
Biological process: negative regulation of transcription by RNA polymerase II; chromatin remodeling
Cellular component: cytoplasm; histone deacetylase complex; nucleus; protein-containing complex; nucleoplasm
Genetic constraint (gnomAD): Loss-of-function variants: 29 observed, 59.18 expected, observed/expected ratio (o/e) 0.49, 90% interval 0.36 to 0.67. The synonymous counts are far from expectation, so gnomAD's model fits this gene poorly and the ratio says little. Missense variants: 701 observed, 706.85 expected, observed/expected ratio (o/e) 0.99, 90% interval 0.93 to 1.06. Synonymous variants: 372 observed, 302.99 expected, observed/expected ratio (o/e) 1.23, 90% interval 1.13 to 1.34.
Homologues: Orthologues: pig MIER2 (82% identical), guinea pig MIER2 (82% identical), chimpanzee MIER2 (81% identical), mouse Mier2 (81% identical), macaque MIER2 (77% identical), rat Mier2 (76% identical), dog MIER2 (76% identical), rabbit MIER2 (69% identical), zebrafish mier2 (33% identical), tropical clawed frog mier2 (25% identical), Drosophila melanogaster CG1620 (16% identical), Caenorhabditis elegans T07F8.4 (15% identical), and 1 more. Paralogues in human: MIER3 (37% identical), MIER1 (33% identical), MTA1 (20% identical), MTA3 (19% identical), MTA2 (17% identical).
Diseases named in the same sentence as MIER2 in open-access papers:
MIER2 is named in the same sentence as 5 diseases in open-access papers, as found by Europe PMC text mining. Sharing a sentence is not in itself a finding about the gene and the disease. The quoted sentences say what the papers report.
colon cancer (1 paper, 2022). "The two highest molar amount genomic regions from our HCT116 colon cancer cells overlap MIER2, part of the MIER gene family, associated with suppression of colorectal cancer." (PMID 36160046, 2022).
renal cell carcinoma (1 paper, 2026).
MIER2 also shares sentences with these, for which no sentence is quoted: cardiac hypertrophy (1 paper); cardiovascular disease (1); colorectal cancer (1).